LIPH (lipase H)
Description:
Hydrolyzes specifically phosphatidic acid (PA) to produce 2-acyl lysophosphatidic acid (LPA; a potent bioactive lipid mediator) and fatty acid. Does not hydrolyze other phospholipids, like phosphatidylserine (PS), phosphatidylcholine (PC) and phosphatidylethanolamine (PE) or triacylglycerol (TG).
Synonyms: mPA-PLA1 alpha; LPDLR; PLA1B; mPA-PLA1; mPA-PLA1alpha; AH; ARWH2; HYPT7; LAH2
Tractability: Antibody: UniProt places it where antibodies can reach, with high confidence; its Gene Ontology location is reachable by antibodies, with high confidence; UniProt predicts a signal peptide or a membrane-spanning region. PROTAC: ubiquitination databases record sites on it.
Gene: Protein-coding gene on chromosome 3 (185,506,262 to 185,552,617, reverse strand). Ensembl gene ENSG00000163898.
Subcellular location: Secreted; Cell membrane
Pathways (Reactome):
Metabolism: Synthesis of PA
Gene Ontology:
Molecular function: heparin binding; phospholipase activity; protein binding; carboxylic ester hydrolase activity; lipase activity
Biological process: lipid catabolic process; phosphatidic acid biosynthetic process; lipid metabolic process
Cellular component: extracellular region; plasma membrane
Genetic constraint (gnomAD): Loss-of-function variants: 15 observed, 28.47 expected, observed/expected ratio (o/e) 0.53, 90% interval 0.35 to 0.81. The upper end of that interval is the gene's LOEUF score, 0.81, which puts it in group 3 of 6, group 1 being the genes least tolerant of losing a copy. Missense variants: 365 observed, 415.31 expected, observed/expected ratio (o/e) 0.88, 90% interval 0.81 to 0.96. Synonymous variants: 144 observed, 151.33 expected, observed/expected ratio (o/e) 0.95, 90% interval 0.83 to 1.09.
Homologues: Orthologues: chimpanzee LIPH (99% identical), macaque TMEM41A (94% identical), pig LIPH (87% identical), dog LIPH (85% identical), rabbit LIPH (84% identical), rat AABR07034648.1 (79% identical), mouse Liph (78% identical), guinea pig LIPH (72% identical), tropical clawed frog liph (61% identical), zebrafish lipia (48% identical), Drosophila melanogaster CG6296 (22% identical), Drosophila melanogaster CG6472 (22% identical), and 13 more. Paralogues in human: LIPI (45% identical), LIPC (31% identical), PLA1A (31% identical), LIPG (31% identical), PNLIP (29% identical), PNLIPRP2 (29% identical), LPL (29% identical), PNLIPRP1 (28% identical), PNLIPRP3 (27% identical).